PIEZO1 (piezo type mechanosensitive ion channel component 1 (Er blood group))
Diseases named in the same sentence as PIEZO1 in open-access papers (continued):
Sharing a sentence is not in itself a finding about the gene and the disease.
Hypertension (continued). "Considering the unique role of Piezo1 in smooth muscle cells and endothelial cells, Piezo1 May be a potential therapeutic target for vascular inflammatory diseases, hypertension-dependent arterial remodeling and fibrosis." (PMID 39425532, 2024). "However, when mechanical stress is abnormal, such as in hypertension or when PIEZO1 is abnormal, pathological myocardial hypertrophy can be induced." (PMID 39272994, 2024). "Piezo1 is involved in the functional regulation and pathophysiological response of the cardiovascular system, and Piezo1 in smooth muscle cells is involved in hypertension-dependent arterial remodeling." (PMID 39425532, 2024). "Multiple studies have shown that Piezo1 has significant effects on vascular development and participates in the physiology and disease states of vascular mechanobiology and related clinical diseases, such as atherosclerosis and hypertension." (PMID 38702777, 2024). "In hypertension, calcium ion entry may be promoted by the activation of mechanosensitive PIEZO1 channels, thereby leading to the decrease in MCV observed in our hypertensive rats." (PMID 37508459, 2023). "This pathway links the Piezo1 channel opening of arterial SMCs to systemic hypertension." (PMID 36439266, 2022). "Although Piezo1 seems to be dispensable for myogenic tone induced by an increase in wall tension, the channel is essential in the arterial remodelling of arteries during hypertension." (PMID 36439266, 2022). "The results showed that Piezo1 protein expression was increased in the atria of both AF patients and SHRs, which was reversed by Val, an effective antihypertensive drug, indicating that Piezo1 might participate in hypertension-induced AF." (PMID 35252406, 2022). "This may be an alternate mechanism for adipogenesis suppression in APVAT preadipocytes; however, more studies are required to determine if PIEZO1 and Wnt16 activation can promote myofibrogenesis of these cells during hypertension." (PMID 36120469, 2022). "Taken together, these findings suggest that Piezo1 could regulate renin expression, and become as a novel drug target for hypertensive diseases." (PMID 36471394, 2022). "In addition, the stretch-activated Ca2+ channel Piezo1 also appears to be prominently involved in hypertension-dependent arterial remodeling." (PMID 35002759, 2021). "Considering the importance of the baroreceptor reflex in cardiovascular disease, targeting Piezo1 and Piezo2 might be a novel strategy for treating hypertension." (PMID 33935792, 2021). "The results of this study and the correlation between hypertension and autoimmune diseases suggest that inhibition of Piezo1 and other mechanosensitive ion channels in T cells may hold therapeutic potential for autoimmune diseases and cytokine release syndromes." (PMID 35260156, 2022). "However, the ability of Piezo1 in atrial myocytes to perceive mechanical stress and its role in atrial electrical remodeling of AF induced by hypertension, especially the regulation of ICa,L, remains unclear." (PMID 35252406, 2022). "Recent studies highlight Piezo‐type mechanosensitive ion channel component 1 (Piezo‐1, PIEZO1) involvement in platelet activation in hypertension." (PMID 39375979, 2025). "However, it is unclear whether Piezo1 is involved in hypertension-induced AF." (PMID 35252406, 2022). "A variety of statistically significant genetic polymorphisms were identified that can be attributed to the heritability of varicose veins affecting inflammation and immunity (eg, PPP3R1, EBF1, and GATA2), hypertension (eg, CASZ1), and vascular architecture (eg, CASZ1, PIEZO1, and STIM2)." (PMID 41391741, 2025). "Hypertension influences the vascular channels, such as TRPV4, Kir2.1, and Piezo1." (PMID 39507419, 2024). "For example, in AS, inhibition of Piezo1 is not the best way to fight AS because it brings about vascular tension and hypertension." (PMID 35154133, 2022).
Hypertension (continued). "During cardiovascular diseases such as hypertension, the PVAT of vessels like the thoracic aorta are subjected to stimulation by potent vasoconstrictors such as angiotensin-II and the activation of their mechanosensors like Piezo1 due to blood flow mechanical forces." (PMID 40277904, 2025). "Thus, the combined actions of both Piezo1 and TRPV4 may contribute to the endothelial vascular barrier dysfunction in hypertension." (PMID 33298523, 2021).
gastric cancer (34 papers, 2014 to 2026). A primary or metastatic malignant neoplasm involving the stomach. "Previous studies have shown that Piezo1 is tightly associated with gastric cancer cell metastasis and proliferation, with relatively higher expression in gastric cancer tissues with omentum metastasis and metastatic lymph node tissues." (PMID 39425504, 2024). "It is also worth mentioning that the Piezo1 chromosomal locus (16q24) when associated with the loss of heterozygosity contributes to the development of gastric cancer." (PMID 36837670, 2023). "Piezo1 knockdown was associated with a downregulation of the integrin β1 expression that remove the migratory capacity of gastric cancer cells." (PMID 32635333, 2020). "Moreover, Piezo1 is blamed for the aberrant proliferative ability of gastric cancer cells, because the knocking down of Piezo1 causes significant G0/G1 arrest." (PMID 36837670, 2023). "For example, in lung adenocarcinoma, Piezo1-Ca2+ signalling initiates the tumour-suppressive ROS/Wnt/β-catenin pathway, whereas in gastric cancer, the same signal cooperates with the YAP1/CTGF pathway to drive pro-fibrotic and inflammatory factor expression." (PMID 41437911, 2026). "Numerous studies have demonstrated that Piezo1 plays a critical role in the mechanically induced proliferation and migration of prostate, ovarian and gastric cancer cells." (PMID 41437911, 2026). "Elevated tumor-specific expression of PIEZO1 has also been reported in prostate cancer and gastric cancer, where PIEZO1 localization was described as both cytoplasmic and membranous." (PMID 40724850, 2025). "In vitro, Piezo1 has been shown to reduce the migratory ability of gastric cancer cells by downregulating integrin β subunits." (PMID 41017814, 2025). "Conversely, in other cancers, such as non-small cell lung carcinoma and gastric cancer, Piezo1 expression is often reduced and has been shown to inhibit cell migration and metastasis, potentially via integrin-mediated and Hippo-pathway-related mechanisms." (PMID 41017814, 2025). "Gastric cancer exhibits a distinct integrin-Piezo1-FAK axis, with rigidity-induced FAK phosphorylation enhancing migration." (PMID 41017814, 2025). "For example, in stomach cancer, Piezo1 works as a potential oncogene by promoting the proliferation and migration of cells involved in gastric cancer." (PMID 38690080, 2024). "For example, in gastric cancer, Piezo1 is a novel trilobal-family-1-binding protein that promotes cancer cell migration in vitro." (PMID 38690080, 2024). "Increased expression of Piezo1 was observed in gastric cancer cell lines and primary samples, and this upregulation was associated with poor disease-specific survival." (PMID 38379701, 2024). "In gastric cancer, there are numerous pathways connected to Piezo1 and its involvement in tumor proliferation, migration, invasion, and angiogenesis." (PMID 36837670, 2023). "Loss-of-function assays shed some light on the molecular mechanisms in gastric cancer in which Piezo1 is involved." (PMID 37762011, 2023). "Piezo1 defects significantly inhibit the oncogenic behavior of gastric cancer cells by downregulating cell proliferation, migration and invasion and enhancing drug sensitivity." (PMID 37762011, 2023). "Piezo1 expression is upregulated in the majority of gastric cancer cell lines, especially those metastasizing to the omentum and lymph nodes, causing poor disease-specific survival." (PMID 36837670, 2023). "Flow cytometry assay results showed that the apoptotic activity of gastric cancer cells was inhibited after treatment with Yoda1 which activates Piezo1." (PMID 36837670, 2023). "Piezo1 has been shown to be a potential proto-oncogene in stomach cancer, one of the most common malignancies." (PMID 36615408, 2022). "Piezo1 overexpression has been observed in several cancers, including bladder cancer, breast cancer, gastric cancers and osteosarcoma." (PMID 35942515, 2022).
gastric cancer (continued). "The detection of Piezo1 upregulation in primary gastric cancer tumor samples suggests a poor prognosis in gastric cancer patients." (PMID 36615408, 2022). "When the expression of Piezo1 is slowed, obvious recompositing of the cytoskeletal system and other morphologic changes in gastric cancer cells lead to the invasion of gastric cancer cells." (PMID 36615408, 2022). "Gastric cancer patients with Piezo1 upregulation also exhibit increased distant metastasis due to enhanced cell proliferation and motility." (PMID 36158191, 2022). "Piezo1 enhances the migration of human gastric cancer cells by modulating the activity of Rho GTPase family members, altering the expression of integrin subunits via Trefoil factor family 1 (TFF1), and inducing the expression EMT-associated genes via HIF-1ɑ." (PMID 36158191, 2022). "Piezo1 knockdown has been observed to decrease migration capacity in gastric cancer cells during in vitro assays through the downregulation of the β1 subunit of integrin." (PMID 34831037, 2021). "In gastric cancer, Piezo1 inhibition through knockdown reduced cancer cell growth and increased the sensitivity of the cells to chemotherapy." (PMID 34831037, 2021). "Piezo1 has been shown to induce HIF-1α expression in gastric cancer cells through calcium influx in response to mechanical force." (PMID 34831037, 2021). "Recent studies have noted the close correlation between the Piezo1 channel and some cancers, including gastric cancer, oral squamous cell carcinoma, prostate cancer, colon cancer, synovial sarcoma, and osteosarcoma." (PMID 33935792, 2021). "A downregulation of Piezo1 or TRPC5 correlates with the accumulation of the active form of Rac1 in gastric cancer and podocyte cells respectively." (PMID 33994356, 2021). "RhoA activity also has a positive correlation with Piezo1 activation, total RhoA is decreased in Piezo1 knockdown gastric cancer cells." (PMID 33994356, 2021). "Overall survival (OS) analysis results suggested that Piezo1 was negatively correlated with shorten OS time of gastric cancer patients." (PMID 33439514, 2021). "The authors reported an overexpression of Piezo1 channels in most of the gastric cancer cell lines analyzed and in primary tumor samples compared with non-tumorous gastric tissues." (PMID 32635333, 2020). "Overall, the results obtained in these papers suggest an oncogenic role for Piezo1 channels in human gastric cells, since they are required for cell proliferation, migration, and invasion to promote gastric cancer progression." (PMID 32635333, 2020). "In gastric cancer, this pathway also involves activation of the Piezo1/YAP1/CTGF axis." (PMID 41437911, 2026). "Furthermore, PIEZO1 acts as a novel trefoil factor family 1 binding protein, enhancing gastric cancer cell movement in vitro." (PMID 40977743, 2025). "Moreover, in peritoneal metastatic tumor tissues of gastric cancer, Piezo1 also regulates the expression of downstream molecules Calpain1/2 by up-regulating HIF-1 and VEGF, promoting tumor angiogenesis and metastasis." (PMID 38690080, 2024). "In addition, Piezo1 knockdown induced G1 phase block in gastric cancer cells and downregulated phosphorylated Rb, Cyclin D1, CDK4, and CDK6, suggesting that Piezo1 is required for gastric cancer cell proliferation." (PMID 38690080, 2024). "As a result of these actions (Piezo1 knockdown and siPIEZO1 transfection), the morphology of gastric cancer cells was different (the cells were elongated and acquired irregular shapes) and the cell motility was reduced, indicating that Piezo1 has an essential role in cancer migration." (PMID 36837670, 2023). "Piezo1 is also highly expressed in gastric cancer, especially when there is peritoneal metastasis." (PMID 37762011, 2023).
gastric cancer (continued). "H. pylori induced NFκB directly regulates PIEZO1 transcription in gastric cancer (GC)." (PMID 37983931, 2023). "Apoptosis of gastric cancer cells is also regulated by Piezo1." (PMID 36837670, 2023). "Gastric cancer growth and its metastases are said to be controlled by Piezo1." (PMID 36837670, 2023). "It was reported that knockdown of Piezo1 in gastric cancer cells led to Rac1 activation." (PMID 35428847, 2022). "In recent years, studies have confirmed that the expression level of PIEZO1 is significantly increased in gastric cancer, esophageal squamous cell carcinoma, glioblastoma multiforme, colon cancer, prostate malignant tumor and bladder carcinoma and decreased in lung cancer." (PMID 35747124, 2022). "Additionally, it was shown that Piezo1 knockdown in gastric cancer cells significantly reduced HIF-1α expression and metastasis." (PMID 34831037, 2021). "Recent research has showed that Piezo1 is involved in TFF1-mediated gastric cancer cell migration." (PMID 32152662, 2020). "Piezo1 is involved in gastric cancer cell migration and invasion." (PMID 32152662, 2020). "A recent study has shown that PIEZO1 regulates epithelial restitution and cell mobility in gastric cancer cells through interaction with trefoil factor family 1 (TFF1), a member of the TFF-domain peptide family; and knockdown of PIEZO1 expression reduces cell migration in gastric cancer cell lines." (PMID 30745454, 2019). "The involvement of PIEZO1 within these processes and conditions results in discernable effects on cancer progression, as high PIEZO1 expression has been shown to correlate with increased migration and chemo-resistance in gastric cancer cells and the increased invasion of osteosarcoma cells." (PMID 38398074, 2024). "In addition, Piezo1 knockdown in gastric cancer tissues leads to GTP-Rac1 hyperactivation thereby interrupting the GTPGDP conversion cycle restriction of Rho protein, which finally causes drastic changes in the shape of the cancer cells and restriction of motility through reduction of stress fibers." (PMID 38690080, 2024). "Furthermore, decrease of Piezo1 expression was also detected in other cancer cells, such as thyroid cancer cells and gastric cancer cells, which may be related to low adhesion and easy migration of cancer cells." (PMID 33318310, 2020). "Likewise, Piezo1 is highly expressed in gastric cancer (GC) tissues with omentum metastasis and metastatic lymph node tissues, suggesting its role in GC omentum metastasis." (PMID 38379701, 2024). "Piezo1 directly interacts with the trefoil factor family 1 (TFF1) protein, enhancing gastric cancer cell migration in vitro." (PMID 37762011, 2023). "There are reports stating that Piezo1 high expression correlates with both lymphatic metastasis and TNM staging of gastric cancer." (PMID 36837670, 2023). "Piezo1 is a binding protein to trefoil factor family 1 (TFF1), contributing to invasion and migration for gastric cancer cells by reducing anoikis, increasing motility, and promoting migration." (PMID 34831037, 2021). "Piezo1’s pleiotropic roles in cancer reflect tissue-specific mechanotransduction programs: pro-fibrotic/pro-tumorigenic in liver diseases, yet tumor-suppressive in NSCLC and gastric cancer." (PMID 41017814, 2025).
osteoporosis (31 papers, 2019 to 2026). A condition of reduced bone mass, with decreased cortical thickness and a decrease in the number and size of the trabeculae of cancellous bone (but normal chemical composition), resulting in increased fracture incidence. "Yoda1 activates Piezo1 to alleviate bone loss in mouse models of ovariectomy and aging, which is a potential therapeutic target for osteoporosis." (PMID 40169556, 2025). "Apart from disuse osteoporosis, Piezo1 activation can also reduce bone loss in OVX and aging mice models." (PMID 38994033, 2024). "Piezo1 knockout results in bone formation failure and stunted bone in adulthood, and consistently, the decrease of Piezo1 channels is one of the causes of osteoporosis." (PMID 37762629, 2023). "Piezoelectric microvibration mitigates estrogen loss-induced osteoporosis and promotes piezo-type mechanosensitive ion channel component 1 (Piezo1), miR-29a, and Wnt family member 3a (Wnt3a) signaling in osteoblasts." (PMID 36831000, 2023). "In conclusion, impaired function of Piezo1 in BMSCs leads to insufficient bone formation especially caused by abnormal mechanical stimuli, and is thus a potential therapeutic target for osteoporosis." (PMID 37759400, 2023). "A genetic impact mapping of human osteoporosis identified several Piezo1 single-nucleotide polymorphisms associated with osteoporosis and fracture, suggesting a potential role for Piezo1 in osteosynthesis." (PMID 36291594, 2022). "In line with this, we found an apparent correlation between the expression level of Piezo1 and the bone loss in osteoporosis patients." (PMID 31290742, 2019). "In human patients with osteoporosis, where bones become brittle with age, a decrease in levels of Piezo1 is correlated with increasing bone loss." (PMID 31290742, 2019). "Deletion of Piezo1 or Piezo2 in osteoblast or osteoclast lineage cells causes a severe osteoporosis phenotype with numerous spontaneous fractures, specifically in osteoblast lineage cells, indicating that Piezo1 and Piezo2 are important in bone formation and bone function." (PMID 38956429, 2024). "However, activation of Piezo1 caused 41% reduction in bone loss in disuse osteoporosis, suggesting that activation of Piezo1 is more effective in the treatment of disuse osteoporosis than in hormone or aging related osteoporosis." (PMID 37759400, 2023). "Nevertheless, our study demonstrates that activation of Piezo1 channel could be considered as a novel target for the treatment of osteoporosis, especially caused by weightlessness or disuse." (PMID 37759400, 2023). "Taken together, our findings precisely elucidate the cellular and molecular mechanisms by which Piezo1 regulates bone loss in weightlessness and thus provides a new therapeutic strategy for pathological osteoporosis, especially caused by weightlessness or disuse." (PMID 37759400, 2023). "Deficiency of Piezo1 in osteoblasts resulted in osteoporosis." (PMID 36568096, 2022). "Human PIEZO1 single nucleotide polymorphisms (SNPs) are associated with body height reduction and may be osteoporosis based on a recent GWAS of UK Biobank." (PMID 32186512, 2020). "Based on this study, mechanical unloading in disuse osteoporosis downregulates Piezo1 in bone marrow mesenchymal stem cells (BMSCs), impairing calcium influx and disrupting the AMPK/SIRT1 pathway." (PMID 41362723, 2026). "Collectively, these findings demonstrate that Piezo1-mediated mechanotransduction constitutes a critical factor by which exercise mitigates osteoporosis and hyperglycemia in T1DM mice." (PMID 42274470, 2026). "While this study delineates the Piezo1-mediated signaling pathway in disuse osteoporosis, several limitations should be acknowledged." (PMID 41362723, 2026).